LINC02761 (long independently transcribed non-coding RNA 2761)
Gene: Long non-coding RNA gene on chromosome 11 (76,210,933 to 76,236,865, reverse strand). Ensembl gene ENSG00000255362.
Gene Ontology:
Molecular function: triplet codon-amino acid adaptor activity
Biological process: translation